MMP9 (matrix metallopeptidase 9)
Diseases named in the same sentence as MMP9 in open-access papers (continued):
Sharing a sentence is not in itself a finding about the gene and the disease.
cancer (continued). "Subsequently, matrix metalloproteinase-9 (MMP-9) is activated, which significantly promotes cancer migration and metastasis." (PMID 35765040, 2022). "Although different markers were used to evaluate EMT in cancers, there was a consistent CCR7-induced increased activation of Slug, N-cadherin, TGF-β, vimentin, phospho-ERK, phospho-Akt, MMP-2, MMP-9 and Snail attenuation of E-cadherin." (PMID 35203305, 2022). "It is also involved in the degradation of ECM by the secretion of MMP-2 and MMP-9, which depicts the importance of ECM and macrophages in the progression of cancer." (PMID 35205204, 2022). "The repressive result of CA on MMP-2 and MMP-9 is connected with the obstruction of NF-κB activation, as identified in liver tumor cells stimulated via PMA, leading to a reduction in cancer invasiveness and growth." (PMID 35355732, 2022). "PRTN3, ELANE, CTSG and MMP9 are the serine proteases released by the activated neutrophils and have been reported to degrade ECM proteins and promote cancer cell invasion." (PMID 36686780, 2022). "The metastasis of cancer cells depends in part on the EMT process and matrix metalloproteinases, such as Snail, MMP2 and MMP9." (PMID 35178453, 2022). "EMT is the pivotal molecular mechanism involved in cancer metastasis, and E-cadherin is the characteristic marker of EMT; however, other markers, including N-cadherin, MMP-9, and SNAI1 are also important for EMT." (PMID 35300562, 2022). "NETs induce gene expression of cancer stem cell marker CD24, and proinflammatory factors, such as IL1β, IL6, IL8, CXC motif chemokine receptor 1 (CXCR1), MMP2, MMP9 in cocultured luminal breast cancer cells." (PMID 35574410, 2022). "In conclusion, regulation of MMP-9 in inflamed IBD tissue and in animal and cell culture models, seems to follow signaling pathways that were also described in cancer and other inflammatory diseases." (PMID 36164340, 2022). "CD147 has been shown to facilitate the secretion of extracellular matrix-degrading metalloproteases from fibroblasts, endometrial cells and cancer cells, such as MMP-1, MMP-3, MMP-9 and membrane type 1-MMP." (PMID 34997863, 2022). "Subsequently, correlation analysis between the expression of LCN2, SLC22A17, and MMP9 genes and RPPA protein levels was performed to identify their involvement in cellular processes and cancer pathways." (PMID 36211450, 2022). "Theexpression levels of MMP-2 and MMP-9 in FPNCE were lower than those in the NCE (p <0.05); the expression levels in the NCE in both cancer cell lineswere the same and showed lower amounts compared to CIS+EPI (p < 0.01)." (PMID 35129960, 2022). "Previous studies have shown that E-cadherin, N-cadherin, vimentin, MMP2, and MMP9 expression levels can indicate EMT and invasion in various cancers." (PMID 35885009, 2022). "These exosomes activate the NF-κB, ERK, and c-FLIPL signaling pathways through the Fas/FasL-dependent trail, leading to MMP2, MMP9, and COX2 increased expression in B16 cancer cells, which play a critical role in cancer cell metastasis." (PMID 35550636, 2022). "Cancer migration/invasion-promoting effects mediated by TLR4 pathways were observed on molecular levels (such as E-cadherin and MMP9) in multiple studies, for study simplicity, we did not evaluate migration-related molecular changes in this study." (PMID 36232715, 2022). "The EtOH extract, EtOAc soluble fraction, and GA extractives impaired the motility and invasion of cancer cells by prohibiting migration and proliferation by the downregulation of MMP2, MMP9, cleaved caspase-3, Bcl-2, and the upregulation of Bax." (PMID 36362345, 2022). "Numerous studies have reported that MMP-1, MMP-2, and MMP-9 enzymes and TIMP-1 and TIMP-2 inhibitors play an active role in angiogenesis, local invasiveness, and metastatic potential of malignant tumors." (PMID 36551933, 2022).
cancer (continued). "The upregulation of KIF3A activates this pathway by increasing DVL2 phosphorylation and β-catenin levels, promoting MMP9 and HEF1 expression and inducing cancer invasion and migration." (PMID 36188577, 2022). "Knowing their significant roles in cancer invasion and migration, the metalloproteinases MMP-2 and MMP-9 were also included in the analysis." (PMID 36613598, 2022). "As detected by in-gel zymography, ectopic MCT-1 expression promoted higher MMP-9 and MMP-2 activities than control cells, and shMnSOD effectively decreased MMP-2 but only modestly reduced MMP-9 in cancer cells compared with the scramble control." (PMID 35017469, 2022). "The activity of matrix metalloproteinases (MMPs) is known to be crucial for cancer cell spread, in particular, MMP-9 triggers the degradation of ECM essential proteins, such as type IV collagen, allowing the spreading of cancer cells." (PMID 36290354, 2022). "The mechanism of action of C9-PEX, through which it antagonizes the interaction of MMP9 with CD44, leads to the suppression of ECM degradation and subsequently cancer cell migration and invasion." (PMID 35406619, 2022). "When activated, they enhance the production of MMP9 via the TLR4/MYD88/NF-κB/AP-1 axis and increase the tumorigenic potential of cancer cells, promoting their immune evasion." (PMID 35406619, 2022). "NETs enhance the expression of EMT markers ZEB1, Snail and fibronectin, cancer stem cell marker CD44, proinflammatory mediators, such as IL1β, IL6, IL8, CXCR1, MMP2 and MMP9." (PMID 35574410, 2022). "DR6 binding to TRAF4 enhances cancer cell mobility by enhancing MMP2 and MMP9 expression and participating in the PI3K/AKT pathway." (PMID 35242717, 2022). "Considering the characteristics of breast molecular subtypes and hormone-positive BC expression of VEGF, research has shown that cancer progression can be arrested or slowed down by targeting TGF-β1, MMP-2, and MMP-9 when irradiated by a proton beam." (PMID 35747793, 2022). "In contrast, when NF-κB translocation and transcriptional activity are inhibited, the expression of MMP2 and MMP9 is reduced and the expression of TIMP-2 is increased, further inhibiting the migration of cancer cells." (PMID 35770085, 2022). "The expression of MMP2 and MMP9 in GB found that the treatment with GSK343 was able to significantly reduce their expression both in vitro and in vivo, counteracting cancer cell migration." (PMID 36430394, 2022). "MMP-9 is a widely investigated MMP, it is involved in cancer cell invasion, tumor metastasis, angiogenesis, and endothelial–mesenchymal-transition (EMT)." (PMID 35955456, 2022). "In the KEGG pathway “proteoglycans in cancer”, the Ras/Raf/ERK/MMP9 cascade, mediated by proteoglycans, is involved in cell proliferation, survival, and angiogenesis." (PMID 35566048, 2022). "The repressive result of CA on MMP-2 and MMP-9 is connected with the obstruction of NF-κB activation as verified in cancer cells induced via PMA, which reduces cancer invasiveness and growth." (PMID 35355732, 2022). "All experimental niosome groups had downregulatedexpression levelsof Bcl2, Drp1, MMP-2, and MMP-9 in both the 4T1 and SKBR3 cancer cellscompared to the control (p < 0.001)." (PMID 35129960, 2022). "Of note is that MIF has emerged as an inducer of cancer cell migration and invasion by up-regulating and activating matrix metalloproteases (MMPs), such as MMP2, MMP9 and MMP13, then contributed to degradation of ECM." (PMID 36703790, 2022). "TNF-α-induced expression of MMP-9 was involved in macrophage fusion and human M13SV1-EGFP-Neo breast epithelial cells × human MDA-MB-435 cancer cell hybridization." (PMID 36555709, 2022).
cancer (continued). "To further examine the prognostic potential of MMP-9 in different cancers, we evaluated the PFI of the 33 cancer types." (PMID 35178444, 2022). "Moreover, it has been well confirmed that G6PD was involved in certain carcinogenesis, and served key roles in extensive cancer cell metabolic reprogramming, including affection the amino acid metabolic pool 43-45, which may in turn provide building blocks for MMP9 protein synthesis." (PMID 34975298, 2022). "On the other hand, SRC, CASP3, EGFR, ERBB2, mTOR, MMP9, and HIF1A followed the proteoglycans in cancer (degree 7)." (PMID 35959427, 2022). "First, we demonstrate the essential function of ADAM8 in the extracellular release of MMP-9 and LCN2, two important mediators of cancer progression in PDAC." (PMID 35216088, 2022). "In cooperation with soluble molecules released by cancer and invasive cells, exosomes stimulate target cells to provide matrix components of the TME, such as exosomes transferring proteases MMP-9 and MMP-13 to the ECM." (PMID 36531059, 2022). "For example, MMP2 and MMP9 can degrade the ECM in TME and destroy the barrier against cancer invasion." (PMID 36611857, 2022). "Functional characterization of all the isolates was evaluated by cytotoxic activity against three cancer cell lines (HCT-116, PC-3, and SK-Hep-1), inhibition of LPS-induced NO production, and inhibition of gelatinolysis by MMP-9." (PMID 35200610, 2022). "This suggests that the upstream regulators of ECM molecules, such as MMP2 and MMP9, and inhibition of EMT can potentially reduce AMPK expression in cancers." (PMID 35770085, 2022). "L1CAM is highly expressed in PDAC cells, the expression levels of which are correlated with cancer progression, metastasis, and neural invasion via the induction of metalloproteinase-2 (MMP-2) and MMP-9 in cancer cells." (PMID 36077804, 2022). "Monocytes and macrophages affect cancer cell extravasation notably via VEGF- and MMP9-mediated EC permeability." (PMID 36248978, 2022). "ZEB1 can promote drug resistance and the survival of cancer cells According to a study, after focal ischemia, gelatinase A (MMP-2) and gelatinase B (MMP-9) activities in the human brain increase." (PMID 36250005, 2022). "Several parameters were tested, including cellular proliferation, cell cycle regulation, apoptosis, relative expression of VEGFR2, EGFR, MMP-9 and CASPASE3 and the protein levels of pVEGFR2 and pSTAT3 in HepG2 cancer treated cells." (PMID 36284117, 2022). "CHE was found to downregulate the expressions of MMP-2 and MMP-9 through the PI3K/Akt/mTOR signaling pathway and change the cytoskeleton structure by reducing p-FAK, which inhibited the metastasis and invasion of cancer in a dose-dependent manner." (PMID 35721116, 2022). "MMP-9 degrades the extracellular matrix for cancer cell invasion, stimulates angiogenesis, and increases VEGF release for cancer cell proliferation and angiogenesis." (PMID 35747809, 2022). "Vimentin, MMP9, FN1, and N-Cadherin are the well-known genes that have the main contribution to metastasis and EMT (Epithelial-to-mesenchymal transition) in cancer." (PMID 35193569, 2022). "Apart from degrading ECM components, MMP-14 is also responsible for the activation of pro-MMP-2, pro-MMP-9, and pro-MMP-13, of which pro-MMP-2 and pro-MMP-9 activation have been claimed as a crucial step in cancer cell invasion and metastasis." (PMID 35586209, 2022). "MMP-9, a member of the matrix metalloproteinases (MMP) family known to confer invasive behavior to cancer cells." (PMID 36307882, 2022). "The network results demonstrated that seven anti-HCC core targets (CASP3, EGFR, ERBB2, mTOR, MMP9, HIF1A, and PPARG) followed the pathways in cancer (degree 7)." (PMID 35959427, 2022). "GO enrichment analysis of MMP9, TIMP1 revealed that these two genes are playing a significant role in metabolic, neurological, cardiovascular diseases and cancers." (PMID 35246549, 2022).
cancer (continued). "ING5 suppresses aggressive phenotypes of various cancer cells via EGFR/PI3K/Akt, IL-6/STAT3, Akt/NF-κB/NF-κB/MMP-9 or IL-6/CXCL12 pathway." (PMID 36425530, 2022). "Seven anti-HCC core targets (CASP3, EGFR, ERBB2, mTOR, MMP9, HIF1A, and PPARG) followed the pathways in cancer." (PMID 35959427, 2022). "The EtOH extract, EtOAc soluble fraction, and gallic acid (GA) extractives impaired the motility and invasion of cancer cells by prohibiting migration and proliferation by the downregulation of MMP2, MMP9, Bax, cleaved caspase-3, and Bcl-2." (PMID 36362345, 2022). "Furthermore, the MMP-9 inhibitory activity was resistant to the digestion process, and is significantly enhanced, thus suggesting a strong potential as a functional food, for effective preventive diets against inflammatory and cancer diseases, especially those related to the digestive system." (PMID 35911116, 2022). "On the other hand, SRC, CASP3, EGFR, ERBB2, mTOR, MMP9, and HIF1A followed the proteoglycans in cancer." (PMID 35959427, 2022). "MMP-2, MMP-7, MMP-9, TIMP-1, and TIMP-2 research has received considerable attention since they play a number of roles in cancer." (PMID 36250005, 2022). "One example is that MMP-9 enhances TGF-β activity, which promotes cancer invasion in metastatic cancers." (PMID 35586209, 2022). "Meanwhile, M2 macrophages can produce various matrix metalloproteinases (MMPs) and chemokines, such as MMP-2, MMP-7, MMP-9, CCL18, and CCL22, which promote the metastasis of cancer cells." (PMID 36685978, 2022). "The expression and activation of the matrix metalloproteinases MMP-2 and MMP-9 are only increased in breast cancer patients, while MMP-2 induces cancer migration." (PMID 35721116, 2022). "Previous in vitro cancer research has highlighted varied effects of MMPs on DPC-proliferation with MMP7 inhibiting cell proliferation and MMP9-inhibition increasing proliferation of satellite cells in dystrophic-muscle." (PMID 35531096, 2022). "In these cancers, KISS1R signalling suppresses metastasis by repressing MMP-9 activity, thereby inhibiting cancer cell invasion and migration." (PMID 35955878, 2022). "Kaempferol inhibited cancer cell invasion by blocking the PKCδ/MAPK/AP-1 cascade and subsequently, MMP9 expression and its activity." (PMID 35379271, 2022). "Matrix metalloproteinase-9 (MMP-9) is an enzyme which belongs to the MMP family, and its activity was related with different stages of carcinoma progression." (PMID 36119505, 2022). "On the other hand, chymase can also cleave pro-matrix metalloproteinase (MMP)-9 to MMP-9, which is well known as a potential biomarker of cancer invasion and metastasis." (PMID 34884420, 2021). "Many studies have used MMP9 and MMP2 as indicators for evaluating cancer cell invasion and migration ability." (PMID 33732651, 2021). "MMP9 is a member of matrix metalloproteinase (MMP) family, which degrades the components of extracellular matrix to promote cancer cell invasion and metastasis." (PMID 34977016, 2021). "Cancer tissues exhibited a higher level mRNA expression of MMP-2 and MMP-9 than pericarcinoma tissues, and this difference was statistically significant." (PMID 31882379, 2021). "Despite MMP-9 overactivation, it has been shown that free TIMP-1 molecules also promote cancer growth." (PMID 34183752, 2021). "MMP-2 and MMP-9, which contribute to cell migration and invasion, have been found upregulated during EMT in cancer cells." (PMID 34743754, 2021). "ADAMTS9-AS1 interference enhanced cancer proliferation and invasion, facilitated levels of KI67, PCNA, MMP-9 and MMP-2, and activated the JAK STAT signaling pathway." (PMID 34900984, 2021). "EGF also increases matrix metalloproteinase 9 (MMP9) activity, which plays a role in cancer progression, cancer invasion and metastasis." (PMID 34115785, 2021).
cancer (continued). "Q-PCR was used to reveal that the transcriptional levels of STAT3-supporting cancer cell-intrinsic hallmarks, including BCL2, MMP9, HIF-1α and PIM1, were all decreased with SPATS2 knockdown in both MHCC-97H and HCC-LM3 cell lines." (PMID 33391405, 2021). "Elevated levels of miR-145-5p resulted in decreased epithelial ovarian and cancer cell migration through MMP2 and MMP9 downregulation." (PMID 33809973, 2021). "The use of chalcones for the treatment of different cancers has also shown that they can reduce cell migration and invasion by reducing MMP-2 and MMP-9 activity through the downregulation of JNK signaling pathways." (PMID 34205043, 2021). "Myr acts as an anti-cancer agent through different mechanisms including the modulation of MMP-2 and MMP-9." (PMID 33498927, 2021). "The activation of MMP-2 and MMP-9 by HMGA1 and the interaction of these MMPs are reportedly important for the growth and invasion of cancer cells in malignant tumors and those of EVTs in the placenta." (PMID 34072941, 2021). "Whereas the most relevant MMPs in this invasive process are MMP-2 and MMP-9, SNAIL was found to induce MMP-9 expression, and EMT was found to be necessary for intravasation of lymph vessels in GBM and other cancers." (PMID 34884812, 2021). "This process is critical for cancer-cell invasion, and it includes the proteolytic degradation of the EM by enzymes such as MMP2 and MMP9." (PMID 35366261, 2021). "In vitro, VM also correlated with increased gene expression of matrix metalloproteinase-9 (MMP-9) and of the cancer stem cell marker CD133." (PMID 34751242, 2021). "The secretion of ECM-remodeling enzymes, such as MMP9 (gelatinase B or type IV collagenase), MMP8 (Neutrophil collagenase or Collagenase 2), CathG and NE, paves the way for cancer cell migration and angiogenesis." (PMID 34572138, 2021). "The presence of cancer cell lines can promote the CAF phenotype in LX-2 as shown by the induction of α-SMA, MMP-9, VEGF, and FGF." (PMID 34885024, 2021). "Regarding cancer metastasis, curcumin and PGV-1 showed inhibitory activities against cell migration and inhibited MMP-2 and MMP-9 protein expression." (PMID 33747866, 2021). "For example, it has been shown that the secretion of pro-inflammatory factors including MMP-9, IL-6 and TGF-β1 from monocytes was upregulated in response to cancer-derived EV stimulation." (PMID 33984826, 2021). "There is generally a tight correlation between HSPB8 and MMP-9 expression, with higher invasive and metastasizing activity in HSPB8 high-expression cancer cells." (PMID 33562660, 2021). "Investigating the role of LUM is a critical field of research in cancer molecular biology because it affects MMP regulation and has been demonstrated to inhibit MMP9 and MMP14 expression." (PMID 34310653, 2021). "By cooperating with HIF-1α in up-regulating MMP9, PERK and HIF-1α also promote migration, helping cancer cells to leave unfavorable environments and escape from cytotoxic agents." (PMID 33423689, 2021). "Our study indicated that VM networks consisting of cancer and CAFs increase N2 neutrophil polarization, which expresses high levels of arginase, CCL2, CXCR4 and MMP-9." (PMID 34485133, 2021). "LCN2 plays a crucial role in the protection of matrix metallopeptidase 9 (MMP-9) from degradation and is upregulated in pathological situations as well as cancer." (PMID 34212049, 2021). "Fucosterol can induce cancer cell apoptosis by increasing the expression of cleaved caspase 3, caspase 9, and Bax and decreasing the expression of Bcl-2, MMP-2, and MMP-9." (PMID 34336128, 2021).